MITF (melanocyte inducing transcription factor)
Diseases named in the same sentence as MITF in open-access papers (continued):
Sharing a sentence is not in itself a finding about the gene and the disease.
melanoma (continued). "KRS binds to microphthalmia-associated transcription factor (MITF) and is involved in the development of melanoma." (PMID 28679377, 2017). "In particular, high expression of MITF in melanoma cells confers high sensitivity to MAPK pathway inhibition, while MITFlow cells are intrinsically more resistant to those treatments." (PMID 29215016, 2017). "Computational analysis demonstrated that OCT4 occupies the promoter and enhancer regions of MITF target genes in melanoma cells and melanocytes and also shares chromatin contact domains with MITF." (PMID 29044103, 2017). "In the present analysis, NRAS-mutant cells activated the AXL program and BRAF/NRAS wild type cells the MITF program which also resembles the melanoma pigmentation subtype described earlier." (PMID 27903987, 2017). "It is notable that TFAP2A levels are decreased in advanced-stage melanoma tumors versus earlier stage melanoma and nevi, whereas MITF expression levels are relatively constant (data from The Cancer Genome Atlas)." (PMID 28249010, 2017). "While during alpha-MSH induced melanocyte differentiation CREB is activated through PKA downstream of the MC1R, we find that in melanoma cells CREB constitutively binds to the MITF promoter and contributes to the basal expression of MITF." (PMID 28380427, 2017). "The hypermethylation of the MITF promoter has been reported in peripheral blood of melanoma patients who develop more than one lesion, and the MITF gene has been observed to be hypermethylated in primary tumors compared to metastatic tumors." (PMID 29100458, 2017). "In melanoma-dominant or melanoma-subordinate pedigrees or in individuals carrying a BAP1, CDK4, CDKN2A, MITF, or POT1 mutation, individuals should be educated on the importance of melanoma prevention and early detection." (PMID 28283772, 2017). "10-HDA inhibited not only the tyrosinase activity, but also the melanogenic enzyme expressions, including tyrosinase, TRP-1 and TRP-2, by suppressing MITF in the B16F10 melanoma cells." (PMID 28793915, 2017). "A recent study of single cell malignant melanoma transcriptomes has further refined these signatures and defined two main transcriptional states of melanoma cells: the MITF and AXL gene programs." (PMID 28060736, 2017). "A recent study demonstrated CRD-BP as an important positive regulator of MITF expression and function in melanoma cell lines." (PMID 28182633, 2017). "Group 2 cells of our study show high expression of MITF- and melanoma-signature genes (PC4 of the study of Tirosh and co-workers)." (PMID 27903987, 2017). "Hypoxia was found to alter the expression of MITF via HIF1α leading to switching of melanoma proliferative to invasive phenotype." (PMID 29383127, 2017). "MITF and its target genes are known to decrease as melanomas gain invasive capacity, and we observed an increase in ILEI along with a decrease in DCT." (PMID 28545079, 2017). "Here, we found that NAT10 knockdown induces cell cycle arrest and suppresses cell proliferation along with the expression of MITF and its target genes related to cell cycle progression in mouse and human melanoma cells." (PMID 28880216, 2017). "Conversely, miR-211, a known transcriptional target of MITF, is induced in melanotic melanoma cells, where it targets EDEM1 and consequently impairs the degradation of TYROSINASE (TYR) through the ER-associated degradation (ERAD) pathway." (PMID 28445987, 2017). "Further, we used TCGA RNA-seq data from cBioPortal to confirm the negative correlation (Pearson’s correlation coefficient: r = -0.217, N = 471, p = 1.94 x 10−6) between ILEI and MITF in melanoma patient samples." (PMID 28545079, 2017). "In melanoma, drugs targeting MITF, such as the HIV1 protease inhibitor nelfinavir, can decrease the formation of loops." (PMID 29149895, 2017). "On the contrary, when MITF expression is lost or de-regulated during melanoma progression, tumor cells tend to evolve towards a dedifferentiated mesenchymal like phenotype." (PMID 29112174, 2017).
melanoma (continued). "Protein analysis of these melanoma cell models prior to injection confirms that MITF has been drastically reduced in these NFIB lines." (PMID 28119061, 2017). "In conclusion, we demonstrate that phenotype switching regulates ILEI expression, and that ILEI regulates partial phenotype switching in MITF-low melanoma cell lines." (PMID 28545079, 2017). "Because CCND1 is transcriptionally regulated by MITF, wogonin was presumed to inhibit CCND1 expression in human melanoma cells by downregulating MITF." (PMID 28182699, 2017). "This supports a regulatory role for TFAP2A not only in differentiation, but across other categories of genes proposed to be regulated by MITF in melanocytes and melanoma, as with the MITF rheostat." (PMID 28249010, 2017). "Treatment of melanoma cells with forskolin was capable to almost fully restore MITF expression under glucose limitation." (PMID 28380427, 2017). "Our data strongly indicated that glucose restriction inhibits melanoma cell proliferation by inducing ATF4 to subsequently interfere with MITF expression in a CRE dependent manner." (PMID 28380427, 2017). "Decreased MITF expression has been described in senescent melanocytes and its downregulation has been shown to promote senescence in melanoma cells." (PMID 28785021, 2017). "To identify a representative cell line, we assessed the AXL and MITF expression status in a panel of melanoma cell lines and their link to response to BRAF inhibition." (PMID 28606996, 2017). "In melanoma, MITF-related loops identified in circulating tumor cells can be used to noninvasively detect cancer and predict a poor prognosis, as shown in humans." (PMID 29149895, 2017). "As MITF is an oncogenic driver in melanomas, identification of therapeutic strategies targeting MITF or its target genes is clinically important for the treatment of melanoma." (PMID 28880216, 2017). "BRN-2 and MITF expression was also detected in melanoma spheres obtained from melanoma cell lines: within each melanosphere, the expression of these two transcription factors was reciprocal." (PMID 29156643, 2017). "A2058 human melanoma cells engineered to over-express either BRN2 or MITF were analyzed by qRT-PCR for expression of all four members of the NFI gene family, NFIA, NFIB, NFIC and NFIX." (PMID 28119061, 2017). "Overexpression of USP13 in melanoma cells prolonged the half‐time of MITF expression in an enzymatic‐dependent manner." (PMID 28544818, 2017). "Previous reports have shown that several small molecules such as HDAC inhibitors, CH5552074, and ML329 targeting MITF reduced the expression of genes involved in pigmentation and cell cycle regulation in primary melanocytes and differentiated melanoma cells." (PMID 28880216, 2017). "The melanoma subtype that is most difficult to target therapeutically, and which is thought to depend on a relatively low level of MITF activity, has stem cell qualities, an invasive phenotype, and an expression profile resembling that of neural crest." (PMID 28249010, 2017). "This cell population, observed in both melanoma cell lines and primary melanoma metastases, is characterized by the low expression of the master regulator of melanocyte differentiation—the MITF." (PMID 29156643, 2017). "This conclusion was reached through CD271 knockdown experiments showing a reduced expression of the transcription factors SOX10 (whose expression was required for maintenance of melanoma CSCs) and MITF (required for melanoma proliferation and invasiveness)." (PMID 29156643, 2017). "The results showed that 10-HDA inhibited the MITF protein expression (IC50 0.86 mM) in B16F1 melanoma cells." (PMID 28793915, 2017). "At bulk‐tumour level, melanomas can be classified as either MITF‐high or AXL‐high, but single‐cell sequencing has revealed intra‐tumour heterogeneity, whereby MITF‐high melanomas also contain cells with elevated AXL expression." (PMID 28606996, 2017).
melanoma (continued). "CDK4 was also part of the PC1, and CDK2 was part of the MITF and melanoma signature in the study of Tirosh and co-workers which is suggestive for a role of both kinases in this study." (PMID 27903987, 2017). "In contrast, a recent study had no inhibitory effects of fucoidan, isolated from the same alga, on TYR, TRP1, TRP2 and MITF expression in B16 murine melanoma cells, although it inhibited cellular melanin and TYR activity." (PMID 28946635, 2017). "Since MITF is very widely expressed in human melanomas, the found that the combination of PDT and Metformin had the ability to inhibit it, along with the inhibition of NF-κB pathway activation seems really promising." (PMID 28278159, 2017). "Along with targeting other oncogenic target genes such as SODD, SMAD1, and MAP4K3, miR-26a inhibited the growth of melanoma cells by directly downregulating MITF." (PMID 28698805, 2017). "In our previous study, a melanoma cell line was treated with NSC-CM to decrease the expression of MITF and melanogenic enzymes." (PMID 29271951, 2017). "Global analysis of differentially expressed genes showed significantly similar pathway alterations following MITF knockdown in all melanoma lines, although the level of overlap in individual genes between MITFhigh and MITFlow lines was low." (PMID 28883623, 2017). "We found that ILEI is highly expressed in MITF-low invasive melanoma cells, and that phenotype switch alters ILEI expression." (PMID 28545079, 2017). "We have determined some of the key signalling players regulating glucose stimulated melanoma cell proliferation, and provide evidence suggesting that the transcription factor MITF acts as a node between glucose metabolism and cell cycle progression." (PMID 28380427, 2017). "MITF is a master gene regulating differentiation of melanocytes, and a lineage survival oncogene mediating pro-proliferative function in malignant melanoma." (PMID 28410220, 2017). "Considering the MITF‐mediated regulation of melanoma cell survival and viability 31, a decreased expression of MITF induced by MTX and FdUrd would make the cells radiosensitive." (PMID 28608446, 2017). "Our data suggests that increased melanoma cell migration in response to elevated NFIB is in part achieved through EZH2 mediated down-regulation of MITF expression." (PMID 28119061, 2017). "Amplification of the MITF oncogene in melanomas has been shown to induce the cell cycle and cell proliferation, as well as inhibit apoptosis." (PMID 28182633, 2017). "To address this issue, we analysed melanoma xenografts derived from the MITF‐expressing cell line A375 (MITF‐high), and as such a population of genetically identical cells." (PMID 28606996, 2017). "Low-MITF expressing populations in melanomas have been described to harbor a slow cycling stem-like population with intrinsic chemoresistant and tumorigenic properties." (PMID 28424421, 2017). "We found in melanoma cell lines that ILEI is highly expressed in MITF-low invasive cells, and that phenotype switching between the MITF-low invasive state and the MITF-high proliferative state can alter ILEI expression." (PMID 28545079, 2017). "Shogaol inhibits α-MSH-induced melanogenesis by accelerating the ERK and PI3k/serine-threonine kinase (Akt) pathways in B16F10 melanoma cells and was also found to downregulate MITF expression." (PMID 29019940, 2017). "Increased MITF was related to a lower prognosis in melanoma patients, resistance to therapies and particularly PDT, while decreased levels were associated with a better PDT therapeutic response." (PMID 28278159, 2017). "We explored solitary (Patient 1) and multiple (Patient T1) melanoma BM with a CD271high phenotype for expression of MITF by co-immunohistochemical staining." (PMID 28852061, 2017).
melanoma (continued). "Upon depletion of MITF in the pretreated cells, the protective effect on non‐pretreated melanoma toward BRAF inhibitors was abrogated." (PMID 28694322, 2017). "MITF activity has also been described as a rheostat that regulates melanoma phenotype by driving senescence at low levels, an invasive phenotype at mid-levels, and melanocyte proliferation and differentiation at higher levels." (PMID 28249010, 2017). "While this seems contradictory in the first place, the explanation lies in the fact that in melanoma cells MITF is a crucial stimulator of cell cycle progression downstream of ERK." (PMID 28380427, 2017). "We reveal that MITF driven communications between melanoma phenotype subpopulations establishes a paracrine protection to BRAF inhibitor therapy, allowing different phenotypes to prevail." (PMID 28606996, 2017). "It was recently reported that MITF regulates melanoma invasion through Rac/Rho GTPases, which supports previous evidence showing MITF is explicitly involved in melanoma progression." (PMID 28424421, 2017). "It was reported that MTX increased MITF expression and induced melanocytic differentiation in melanoma cells." (PMID 28745431, 2017). "The phosphorylation and activation of p38 MAPK in B16 melanoma cells was found to increase melanin synthesis through increased expression of MITF and TYR via CREB phosphorylation." (PMID 28946635, 2017). "When melanoma cells with high MITF levels were transfected with a vector for expression of OCT4 there was a reduction of both TRPM1 and TYR expression." (PMID 29044103, 2017). "Melanomas that regress with MAPK pathway inhibitors are characterized by the expression of the lineage‐specific transcription factor MITF." (PMID 28606996, 2017). "The expressions of TRP-1, TRP-2, and MITF were all inhibited in the B16F10 melanoma cells, which were treated with 10-HDA." (PMID 28793915, 2017). "Our recent study showed that NSC-CM increased depigmentation via the inhibition of Wnt/β-catenin signaling pathway by triggering DKK1 upregulation in a melanoma cell line and subsequent downregulation of the expression of MITF and melanogenic enzymes." (PMID 29271951, 2017). "Melanogenesis and melanoma progression are interconnected by activation of wingless (WNT), melanocortin 1 receptor (MC1R, Gene ID: 4157), and melanogenesis-associated transcription factor (MITF, Gene ID: 4286) signaling." (PMID 28265786, 2017). "Ascorbic acid stimulates melanogenesis in B16F10 murine melanoma cells by expression of MITF, tyrosinase, TRP-1, and TRP-2, as well as activation of the MAPK family, accelerates p38 activation and suppresses activation of JNK and ERK." (PMID 29019940, 2017). "Isosakuranetin, an important component of propolis, Baccharis dracunculifolia, Terminalia fagifolia, Citrus sinensis, was proved to stimulates melanogenesis in B16 melanoma cells via up-regulation of MITF." (PMID 28777326, 2017). "The low expression of MITF is functionally relevant for these cells, as supported by the observation that inhibition of MITF expression in melanoma cell lines increased the tumorigenic potential and the expression of stemness markers such as OCT4 and Nanog." (PMID 29156643, 2017). "On the other hand, activation of cAMP signalling or low MITF/AXL expression ratio are involved in melanoma acquired resistance to vemurafenib." (PMID 29299138, 2017). "Ki‐67 and MITF staining analysis of corresponding tissue sections showed a clear correlation between cellular ITdU uptake and the proliferation signature of the melanoma cells." (PMID 28608446, 2017). "Previous reports have suggested that the pro-angiogenic response of melanoma to low levels of oxygen depends at least in part on HIF1α mediated down-regulation of MITF." (PMID 28380427, 2017). "In the context of melanoma, heterogeneity between two transcription factors, BRN2 and MITF, has been associated with phenotypic switching between predominantly invasive and proliferative behaviors respectively." (PMID 28119061, 2017).
melanoma (continued). "Heterogeneous expression of the Microphthalmia-associated Transcription Factor (MITF) and the POU domain transcription factor BRN2 (POU3F2) has been found in malignant melanoma." (PMID 28883623, 2017). "Differential expression of selected molecules in melanoma cell lines following knockdown of MITF or BRN2 was confirmed using qRT-PCR." (PMID 28883623, 2017). "Some miRs directly target important transcription factors, such as miR-200 regulation of ZEB in epithelial carcinomas, while in melanoma, miR-148 mediated dysregulation of MITF and miR-125b control of JUN have been noted." (PMID 27852308, 2016). "Lebein is able to modify intracellular levels of MITF, imposing a change in the phenotype of melanoma cells from proliferative to differentiated and noninvasive." (PMID 27399772, 2016). "Other studies provide supportive evidence to this claim and show that TGF-b signaling can mediate MITF expression, which is critical for the generation and maintenance of melanoma stem cells." (PMID 27566591, 2016). "Recent studies have identified the existence of slow-cycling, low MITF-expressing CICs in melanoma cell populations with intrinsic chemoresistant and tumorigenic phenotypes." (PMID 27566591, 2016). "In this study, we have demonstrated that the ERBB3 receptor and its cognate ligand NRG1-beta are elevated after MITF depletion in various melanoma cell lines." (PMID 27391157, 2016). "We identified MiTF as a critical regulator of the FANC pathway in melanoma and demonstrated that MiTF-silenced cells display the primary characteristics of FA cells, i.e., the cellular and chromosomal hypersensitivity to ICL-inducing agents." (PMID 27827420, 2016). "They demonstrated that p21 regulated the promoter of microphthalmia-associated transcription factor (MITF), a transcription factor which plays a central role in the expression of melanocyte-specific genes, lineage determination, and survival of melanoma cells." (PMID 26621850, 2016). "MITF suppression was already reported as accompanying a lineage-specific senescence program in melanoma cells." (PMID 26824319, 2016). "The upregulation of MITF correlated with increased expression of its target genes TYR and MLANA, which is in line with previous observations of increased melanoma differentiation antigen expression on treatment, and indicates that MITF is functional." (PMID 26977879, 2016). "As previously observed for human melanoma cell lines, 3 days after transfection both MiTF and Fancd2 siRNA reduced their corresponding protein expression level and MiTF siRNA in B16-F10 triggered a G0/G1 cell cycle arrest." (PMID 27827420, 2016). "We pooled the top and bottom 25 % of melanoma samples according to MITF expression into the MITF+ and MITF– sets, respectively (96 samples per set)." (PMID 27535130, 2016). "TYRO3 induces MITF-M expression in a SOX10-dependent manner in melanoma cells, while other studies showed the anti-correlation between MITF and AXL in melanoma cells." (PMID 27102439, 2016). "We report here that the FANC pathway plays an unexpected yet key role in the proliferation and survival of melanoma cells downstream of MiTF." (PMID 27827420, 2016). "They proposed that an intermediate, well-balanced MITF level is important for melanoma cells to survive and proliferate." (PMID 26927636, 2016). "MITF protein levels vary between melanoma specimens, which is also reflected in the present study performed in patient-derived populations." (PMID 26824319, 2016). "We found that melanoma cell lines retained the MITF phenotype of the corresponding lesions, but both MITFhi and MITFlo cell lines and short term cultures were found in each of the three susceptibility groups (data not shown)." (PMID 26678033, 2016). "Here we showed that this dependency relies in a cluster of genes selectively enriched in melanoma, a feature we functionally demonstrated for MITF and RAB27A." (PMID 27857118, 2016).